NPR1 (natriuretic peptide receptor 1)
Diseases named in the same sentence as NPR1 in open-access papers (continued):
Sharing a sentence is not in itself a finding about the gene and the disease.
infection (continued). "Consistent with the previous studies, Pp-NPR1 and other genes related to SA biosynthesis and signaling were significantly upregulated in pear leaves along with the infection by both C. fructicola strains." (PMID 35251071, 2022). "FRK1 mRNA levels were severely reduced in ald1npr1 and ald1sid2 at 10 and 20 h after PsmES4326/AvrRpt2 infection compared with ald1, npr1 and sid2, respectively." (PMID 36523630, 2022). "In this study, WRKYs emerged as a major group of TFs showing differential expression in response to D383 infection, further supporting a potential role for NPR1 in Gpa2-mediated plant immunity." (PMID 35783958, 2022). "During pathogen infection, SA directly binds to NPR1 to regulate its activity and stability, which is essential for its downstream activation of effector proteins/genes." (PMID 35154230, 2022). "NPR1 mutation resulted in reduced SA accumulation, and PR1 transcription after PsmES4326/AvrRpt2 infection at 10 h and 20 h after inoculation compared to WT plants." (PMID 36523630, 2022). "This indicated that both cultivars initiated the NPR1 resistance mechanism to resist infection from pathogens." (PMID 35392815, 2022). "Considering the additive effect between ALD1 and NPR1 or ICS1/SID2, the results strongly support that ALD1 can impact PR1 expression during infection in a SA- and NPR1-independent manner using a constitutive defense mutant." (PMID 36523630, 2022). "The working principal was an oligomer form of the NPR1 protein that gets converted to a monomeric form after pathogen infection and moves to the nucleus where it activates defense-related genes." (PMID 36616289, 2022). "The SA and PR1 mRNA levels significantly decreased in the infected leaves of the ald1npr1 mutant after PsmES4326/AvrRpt2 infection compared with those in ald1 and npr1 mutants." (PMID 36523630, 2022). "Previously, it was reported that the npr1 mutant showed stronger HR than the WT after infection with P. syringae carrying AvrRpm1 (OD600 = 0.03 or 0.1), but exhibited a WT-like response to P. syringae carrying AvrRpt2 (OD600 = 0.03)." (PMID 36523630, 2022). "Correspondingly, NPR1 has been widely shown to be involved in resistance to viruses, and it is therefore reasonable to suggest its participation in the response to infection by SCYLV." (PMID 34344928, 2021). "By employing npr1 mutant plants in infection assays, we now assessed the role of NPR1 in NHP-induced resistance against the compatible Hpa isolate Noco2." (PMID 33871649, 2021). "In local pathogen infection, high levels of SA induce defense gene expression by activating the transcriptional activator NPR1 and lead to cell death." (PMID 34630489, 2021). "When the biotic and abiotic infection, SA will combine with its receptors (NPR1, NPR3, and NPR4) and induce the expression of PR protein, which leads to trigger the immune responses." (PMID 35003927, 2021). "Infection by pathogens results in the accumulation of SA and NPR1 oligomer-to-monomer reaction through SA-mediated redox changes in the cell, allowing NPR1 to migrate into the nucleus." (PMID 34829975, 2021). "Before the pathgen infection, the content of SA is low in the plant, and NPR1 localizes in the cytoplasm as inactive oligomer through disulfide bonds." (PMID 35003927, 2021). "In this study, increased expression of NPR1 was observed with KPF treatment at the early stage of infection, but later and lower expression was observed in the control group." (PMID 35082814, 2021). "Most NPR1 studies have examined the intracellular localization of NPR1 after 24 h of pathogen infection or SA treatment, indicating that import of NPR1 into chloroplasts at an early time point after abiotic and biotic stresses has not been investigated." (PMID 32152424, 2020). "After 24 h of infection, the NPR1 expression was reduced in infected and uninfected OxCM and WT plants." (PMID 33177639, 2020).
infection (continued). "The result showed that the level of free GFP in GFP-ATG8a and npr1 (GFP-ATG8a) increased with the time of AvrRpt2 infection and both reached the maximum at 6 h, but decreased significantly at 12 h." (PMID 32708160, 2020). "The results showed that NPR1 was significantly induced in the OxCM infected plants compared with the level in WT infected plants and the expression increased with increasing infection time until 24 h." (PMID 33177639, 2020). "Changes in SA concentration after pathogen infection affect the redox state of the cell and bring about a conformational switch of NPR1 and thereby activate PR genes." (PMID 32457781, 2020). "SAR is established against infections by biotrophic and hemibiotrophic pathogens, with the NPR1 gene as a key regulator in this pathway; in Arabidopsis, the NPR1 protein is located in an inactive oligomeric form in the cytoplasm in the absence of pathogens." (PMID 32265961, 2020). "Pathogen infection triggers alteration of cellular reduction potential, thereby reducing NPR1 tetramer into a monomer via breakage of disulfide bonds, after which NPR1 monomer is imported into the nucleus to function as a coactivator of gene transcription." (PMID 32152424, 2020). "Treatment of S plants with RS extract challenged NPR1 expression with a simultaneous PR1 upregulation at the first 2 d of pathogen infection following a reverse pattern at 4 d." (PMID 32098979, 2020). "The npr1 mutant Arabidopsis plants fail to induce SAR in response to various inducing agents and display increased susceptibility to pathogen infections." (PMID 33042179, 2020). "As the SA concentration increases upon pathogen infection or exogenous application of SA, oligomerized NPR1 is reduced to monomers in the cytosol and translocated into the nucleus." (PMID 32865553, 2020). "At 2 d.p.i of AvrRpt2 infection, the leaves of rps2 and atg4a4b were only yellowed, while the leaves of npr1 and atg8a were especially degraded." (PMID 32708160, 2020). "NPR1 is a co-activator protein whose status is tightly controlled by redox changes occurring after pathogen infection or SA treatment." (PMID 31428113, 2019). "Upon bacterial pathogen infection, the npr1 plants accumulated significantly higher levels of ICS1 transcripts and free SA than the wild-type plants." (PMID 30720746, 2019). "Bloating of the intestinal lumen upon pathogen infection activates the NPR-1/GPCR and DAF-7/TGF-β pathways, which results in a preference towards high oxygen." (PMID 31674907, 2019). "Partially reduced NPR1 oligomers become monomers under pathogen infection, and this process triggers SA accumulation." (PMID 30857376, 2019). "With confirmation of the expressions of glyoxalase-like genes in grape, PR1 and NPR1 (involved in the defence response) and VvGAPHD (a housekeeping gene) were evaluated by qRT-PCR following infection with P. viticola." (PMID 31072302, 2019). "Instead, bloating of the intestinal lumen caused by the pathogen infection underlies the avoidance behavior via modulation of both DAF-7/TGF-β and the G-protein coupled receptor NPR-1 neuroendocrine pathways, which regulate aerotaxis." (PMID 31674907, 2019). "Peculiarly, once the plant has detected an infection it builds resistance by destroying the NPR1 protein." (PMID 31589140, 2019). "The PR1 and NPR1 transcripts in transgenic plants were 3.3–3.8-fold higher than those in WT plants before pathogen infection." (PMID 31747891, 2019). "However, upon pathogen infection or treatment with exogenous SA, a change in the cellular redox system occurs, that has been associated with the SA-triggered suppression of JA responses, which induces NPR1-complex dissociation to monomers, by the reduction of disulfide links." (PMID 31057566, 2019). "In this study, we identified that NH1, a rice homolog of NPR1, was significantly induced in OsWRKY67 overexpressing plants relative to Nipponbare plants both before and after pathogen infection." (PMID 30367631, 2018).
infection (continued). "Upon pathogen infection, SA-triggered redox changes will lead to reduction of NPR1 disulfide bridges." (PMID 30444888, 2018). "The diminished AR to M. oryzae observed in the HvNPR1-Kd transgenic line indicated a key role of NPR1 during the AR triggered by P. syringae DC3000 infection." (PMID 30386355, 2018). "During pathogen infection or SA treatment, the NPR1 complex disarticulates, and monomeric proteins are transported into the nucleus." (PMID 29581883, 2018). "Upon pathogen infection, the increase in SA results in reduction of disulfide bonds in NPR1, monomerization, and subsequent translocation to the nucleus, where NPR1 activates the expression of PR genes." (PMID 30563149, 2018). "Induced SA upon pathogen infection results in cellular redox potential change, which triggers the reduction of cytosolic oligomeric NPR1 into monomeric NPR1." (PMID 30154809, 2018). "Strong downregulation of PR1 and PR5 in untreated ap2c1 plants, and high upregulation at 4 hpi with Pto is remarkable, even though after infection a negative regulator of NPR1-mediated PR gene induction, namely NIMIN1, is upregulated." (PMID 28062592, 2017). "NPR1 is constitutively expressed in plants, and its expression level is elevated upon SA treatment or pathogen infection." (PMID 28553307, 2017). "We applied this protocol to investigate the effect of the NPR1 gene silencing to changes in Arabidopsis thaliana plants following Pseudomonas syringae pathovar tomato strain DC3000 infection." (PMID 29169324, 2017). "Arabidopsis npr1 mutants fail to activate immunity following SA treatment or pathogen infection, indicating NPR1’s critical importance for SA signaling." (PMID 28335774, 2017). "Despite carrying the allele for NPR-1 215F, RC301 animals showed an enhanced resistance to infection by the bacterial pathogen P. aeruginosa compared to the DA650 strain, an RC301 derivative that carries the allele for NPR-1 215F in the N2 background." (PMID 28179390, 2017). "Leaf bacteria spore count (phenotype) dataset of 31 Arabidopsis wild type (control) and 29 npr1 mutant (case) plants 48 h post Pst-DC3000 infection." (PMID 29169324, 2017). "After infection, SA-induced changes in the cellular redox state reduce NPR1 to monomers that are transported to the nucleus." (PMID 28335774, 2017). "NPR1 is stabilized in cells peripheral to the infection site where SA concentration is too low for NPR3-NPR1 interaction but high enough to disrupt NPR4-NPR1 interaction." (PMID 27513560, 2016). "During the pathogen infection, the expression of NPR1 mRNAs was down-regulated in the black pepper plants." (PMID 27313593, 2016). "Our previous also showed that infection of TYLCV induced the NPR1 expression and reduced the JA downstream gene expression." (PMID 27103351, 2016). "In Theobroma cacao plants knocked down with a synthetic miRNA targeting TcNPR3 mRNA, a repressor of NPR1 was reported to be more resistant to the infection of P. capsici." (PMID 27313593, 2016). "Recently, NPR1, as a regulator protein, is required in development of induced resistance induced by pathogen infection." (PMID 27054585, 2016). "Because this PCD-associated immune response is tightly restricted to the site of infection, there is likely a threshold at which NPR1 is degraded to relieve its repression on cell death." (PMID 27513560, 2016). "On the other hand, the resistant cultivar, such as Vandana had shown substantial upregulation of SA biosynthesis and responsive (NPR1-mediated) genes in the infected roots during both early and late infection of RKN." (PMID 26961568, 2016). "NPR1 degradation occurs in cells with high SA concentration (infection site) to remove its inhibition on ETI and PCD." (PMID 27513560, 2016). "NPR1 is a key regulator of gene expression following infection and controls the onset of the immune response known as SAR." (PMID 26398891, 2015).
infection (continued). "Increases in SA levels after pathogen infection alter the cellular redox state, triggering a reduction of NPR1 by thioredoxins that leads to the dissociation of NPR1 into monomers." (PMID 26042138, 2015). "Recently, NPR1, as a regulator protein, is required in development of induced resistance induced by SA or pathogen infection." (PMID 25811367, 2015). "NPR1, as a regulator protein, is required in development of induced resistance induced by SA or pathogen infection." (PMID 25811367, 2015). "Accumulation of PR-1 transcripts in NahG transgenic plants, eds16–1 and npr1–1 mutants were lower than those in Col-WT, ein2–12 and jar1–1 mutants during the early phase of infection (10 h post inoculation)." (PMID 25565273, 2015). "Approximately 35,000 M2 plants from an ethyl methanesulfonate-mutagenized population (20 pools, each from ~500 M1 plants) in the npr1-3 mutant background were individually analyzed for free SA levels after infection with the bacterial pathogen Psm ES4326." (PMID 25610446, 2014). "The abundance of infection-induced DSBs was reduced by salicylic acid and NPR1-mediated defenses, and by certain R gene-mediated defenses." (PMID 24699527, 2014). "The Lox gene was induced dramatically whereas expression of Npr1, a gene up-regulated by SA, decreased slightly in DN-AtRop1 transgenic plants after infection with P. infestans." (PMID 25547733, 2014). "Developing flowers of homozygous npr3 mutants are dramatically more resistant to infection by the pathogenic bacterium Pseudomonas syringae, suggesting a role of NPR3 as a repressor of NPR1-mediated defense response with a novel role in flower development." (PMID 24314063, 2013). "In Arabidopsis, NPR1 plays a major role in the SA pathway by regulating more than 99% of SA/BTH-regulated genes, while NPR1-independent pathway(s) also operate during early phases of pathogen infection." (PMID 24093634, 2013). "Necrosis upon infection with Xcv ΔxopJ was greatly reduced in pepper plants with reduced expression of NPR1, a central regulator of SA responses, demonstrating the involvement of SA-signalling in the development of XopJ dependent phenotypes." (PMID 23785289, 2013). "ADPWH_lux-based SA estimation, and allowed the screening for npr1 suppressors that accumulated less SA than npr1 after pathogen infection in a high-throughput manner." (PMID 20863393, 2010). "To further confirm that the suppressors accumulate less SA than npr1 after pathogen infection, we measured SA levels in the suppressors using HPLC." (PMID 20863393, 2010). "We adapted this protocol to a high-throughput format and identified six npr1 suppressors that accumulated lower levels of SA than npr1 upon pathogen infection." (PMID 20863393, 2010). "ATG6 synergistically inhibits the infection of Pst DC3000/avrRps4 with NPR1." (PMID 40036061, 2025). "Notably, the KO lines showed reduced expression of critical pathogenesis-related genes (PR1a, PR5, NPR1) after infection." (PMID 40650151, 2025). "Interestingly, ATG6 overexpression significantly increased the formation of SINCs-like condensates, which should also be a way for ATG6 and NPR1 to synergistically resist infection of pathogens." (PMID 40036061, 2025). "However, during later stages of infection, transgenic plants showed reduced levels of the NPR1, WRKY45, PR1a and PR10a genes, along with decreased H2O2 accumulation, while SA levels remained unchanged." (PMID 41225863, 2025). "NPR1-based resistance has been employed in many crops to control pathogen infection." (PMID 39161600, 2024). "Here, we report that NPR1 plays a pivotal role in restricting compatible infection by turnip mosaic virus, a member of the largest plant RNA virus genus Potyvirus, and that such resistance is counteracted by NUCLEAR INCLUSION B (NIb), the viral RNA-dependent RNA polymerase." (PMID 37328517, 2023).
infection (continued). "Interestingly, we observed water-soaking in the inoculated leaves of npr1-1 and sid2-2 mutant plants at 24 h post-infection (hpi) under both LD and LL conditions, whereas wild-type plants showed water-soaking only under LD conditions." (PMID 36759607, 2023). "However, in our case, the transcription level of TGA2 was low after pathogen infection, as result of which the complex formation of NPR1 and TGA2 is hindered." (PMID 36968378, 2023). "Upon pathogen infection, SA is synthesized through the isochorismate pathway and perceived by two groups of receptors, NPR1 and NPR3/NPR4, to regulate plant systemic acquired resistance (SAR), PAMPs-triggered immunity (PTI), and effector-triggered immunity (ETI)." (PMID 38186590, 2023). "The NPR1 transcript levels were also elevated after the pathogen infection." (PMID 36968378, 2023). "High SA levels during pathogen infection release NPR1 which is a key regulator of SAR42,43." (PMID 38097579, 2023). "NPR1, a key gen regulator for transducing the SA signaling and activating PR gene expression in the pathway, and both exogenous SA application and pathogen infection may lead to enhanced expression of the NPR1 gene of the SAR pathway in plants." (PMID 36938065, 2023). "It is currently not known whether other microbial pathogens, such as viruses, modulate NPR1 to benefit infection." (PMID 37230965, 2023). "However, upon infection, the SA content increases and NPR1 switches to an active state and is transferred to the nucleus to regulate gene expression." (PMID 38003355, 2023). "Populations of the attenuated strain were higher in npr1 and sid2 mutants than in the WT plant, and a further mutation of ALD1 in npr1 and sid2 mutants did not render plants more susceptible to PstDC3000 ΔAvrPto/ΔAvrPtoB infection." (PMID 36523630, 2022). "Upon pathogenic infection, increasing cellular concentration of SA leads to the dephosphorylation of Ser55/Ser59 and SUMOylation at the SUMO-interacting motif 3, which triggers the phosphorylation of Ser11/Ser15, in NPR1." (PMID 35154230, 2022). "Furthermore, compared with wild-type Arabidopsis thaliana, the morbidity level of ΔAtCAMTA was increased after infection with F.graminearum, and the expression level of NPR1 was significantly reduced." (PMID 35887481, 2022). "For example, the most studied form of IR is systemic acquired resistance (SAR, Ross, 1961; Durrant and Dong, 2004), which is triggered by a localized infection with necrotizing pathogens and has been demonstrated to require both the SA hormonal pathway and NPR1." (PMID 34630455, 2021). "Moreover, the lengths of IH/cm2 leaf surface were about twice as high as those of naïve Col-0 plants, and the npr1 leaves also carried a higher number of oospores than Col-0 leaves at this stage of infection." (PMID 33871649, 2021). "NPR1 function is reduced from an oligomeric state to a monomeric state and is then translocated to the nucleus after the accumulation of SA induced by pathogen infection." (PMID 34502265, 2021). "As salicylic acid (SA) concentration in the cell increases under pathogen infection, the NPR1 complex is decomposed and translocates into the nucleus, interacts with the TGA factors to induce the transcription of the antimicrobial PR genes, and enhances general resistance." (PMID 34502265, 2021). "NPR1 could accelerate the senescence or infection-induced accumulation of ubiquitinated proteins and endoplasmic reticulum stress in atg2." (PMID 34829975, 2021). "Moreover, the NPR1 transcript levels are induced two- to threefold upon pathogen infection or salicylic acid (SA) treatment, but the biological relevance of the induction is unclear." (PMID 33072146, 2020). "The SA pathway is especially active following infection by biotrophic pathogens and which stimulates the transcription of NPR1 which in turn leads to activation, as well as accumulation, of SA-induced PR signature gene (PR1, PR2, and PR5) products locally and systemically that leads to SAR." (PMID 32765538, 2020).